LINC02208 (long independently transcribed non-coding RNA 2208)
Synonyms: HRAT56
Gene: Long non-coding RNA gene on chromosome 5 (118,000,253 to 118,562,203, reverse strand). Ensembl gene ENSG00000250891.
Diseases named in the same sentence as LINC02208 in open-access papers:
LINC02208 is named in the same sentence as 1 disease in open-access papers, as found by Europe PMC text mining. Sharing a sentence is not in itself a finding about the gene and the disease.
LINC02208 shares sentences with these, for which no sentence is quoted: testicular cancer (1 paper).